IGF1 (insulin like growth factor 1)
Diseases named in the same sentence as IGF1 in open-access papers (continued):
Sharing a sentence is not in itself a finding about the gene and the disease.
sarcopenia (continued). "In addition, decreased serum IGF-1 levels are independently associated with the risk of sarcopenia and increased abdominal visceral fat." (PMID 35250869, 2022). "Therefore,the findings of this study indicate that circuit exercise has a positive effecton the improvement of cardiovascular risk factors, vascular inflammatory markers,and IGF-1 in elderly obese women with sarcopenia." (PMID 39076242, 2022). "Serum IGF-1 levels are associated with sarcopenia, and frailty." (PMID 36078393, 2022). "During the aging process, levels of testosterone and insulin-like growth factor-1 could significantly decrease in males that leading to a rapid loss of muscle mass and strength, which significantly increase the risk of sarcopenia." (PMID 35909561, 2022). "Plasma IGF-1 decreases with age, and low IGF-1 levels are associated with sarcopenia risk." (PMID 35011721, 2022). "These sex-dependent susceptibilities may be caused by a marked decline in insulin-like growth factor-1, one of the key factors in the pathophysiology of sarcopenia, which was more prominent in men than in women." (PMID 35370897, 2022). "Dysregulation of the IGF-1 anabolic signaling cascade and resultant sarcopenia may be caused by dysbiosis of the gut microbiome and depletion of IGF-1-related microbes such as lactobacilli, possibly the L. Plantarum." (PMID 35010928, 2021). "Sarcopenia in malnutrition/cachexia may be associated with lowering of IGF1 levels in muscle tissue or plasma." (PMID 34220703, 2021). "Dysregulation of the IGF-1 anabolic signaling cascade and resultant sarcopenia may be caused by dysbiosis of the gut microbiome and depletion of IGF-1-related microbes such as lactobacilli and speculatively L. plantarum." (PMID 33672207, 2021). "IGF-1 is known to be an independent risk factor for sarcopenia, and a decrease in GH, estrogen, and dehydro-epiandrosterones, a precursor of testosterone, is known to be the cause of sarcopenia." (PMID 33573198, 2021). "Uremic sarcopenia is mainly related to the comorbidities typical of uremia: metabolic acidosis, low-grade chronic inflammatory state, vitamin D deficiency, IR, hormonal alterations (in particular testosterone, IGF-1 and cortisol) and gut dysbiosis." (PMID 33406683, 2021). "Sarcopenia is associated with not only numerous hormonal factors, including insulin-like growth factor-1 (IGF-1), insulin, testosterone, and oxytocin but also nutritional factors such as trace elements, vitamin D, protein, leucine, polyunsaturated fatty acid (PUFA), and body mass index (BMI)." (PMID 32695733, 2020). "In this study, we demonstrated that the prevalence of sarcopenia among the patients with LC was 28.6% and confirmed our previous findings that lower serum levels of BCAA and IGF-1 were significantly and independently associated with sarcopenia in patients with LC." (PMID 33050430, 2020). "The results suggest that GH and IGF-1 are associated with sarcopenia in the elderly." (PMID 32264885, 2020). "In the present study, we demonstrated that baseline serum BCAA and IGF-1 levels were associated with sarcopenia and slow gait speed, and that they may be surrogate markers for predicting these complications in patients with LC." (PMID 33050430, 2020). "However, the present study did not examine the myostatin levels and the association of myostatin with BCAA, IGF-1, and sarcopenia." (PMID 33050430, 2020). "Furthermore, on the basis of baseline serum BCAA or IGF-1 levels, we classified the patients into three groups and investigated the association of these levels with sarcopenia and slow gait speed." (PMID 33050430, 2020). "In addition, increasing evidence suggests that the age-related effects of GH, IGF-1, androgen, and estrogen are associated with the incidence and pathogenesis of sarcopenia." (PMID 32264885, 2020).
sarcopenia (continued). "Even though supplementation with IGF-1/GH is associated with an anabolic effect expected at the muscular level, only a minor response has been raised in other aetiologies of sarcopenia such as ageing-induced sarcopenia." (PMID 29724029, 2018). "This noted impairment in exercise‐induced miRNA regulation with aging and the associated inhibition of the IGF‐1 signaling may provide a mechanism for age‐related muscle loss such as sarcopenia." (PMID 28597569, 2017). "Moreover, both low selenium and IGF-1 levels are associated with anemia, another potential determinant of sarcopenia." (PMID 24152751, 2013). "Recent surveys indicate that polymorphisms in genes controlling muscle mass in humans and mammals, including the genes encoding insulin growth factor 1 (IGF1), myostatin, follistatin and components of the activin receptor protein complex, are linked to increased risk of sarcopenia." (PMID 24092876, 2013). "The reduction of IGF-1 levels is associated with sarcopenia, frailty, and mortality." (PMID 20480032, 2010). "Therefore, IGF-1 may be expected to be a biomarker for hyponatremia-induced sarcopenia and bone loss, although there is limitation that serum IGF-1 level is influenced by IGF-1 derived from organs other than skeletal muscles." (PMID 40227313, 2025). "The gender distribution of susceptibility to sarcopenia may be attributed to faster muscle degeneration in men and a gradually fat increase in women during aging, and the change pattern in estrogen, testosterone and insulin-like growth factor-1 levels." (PMID 38825679, 2024). "Therefore, analysis of the relationship between IGF-1 levels and LS may help understand the pathogenesis of sarcopenia associated with liver disease." (PMID 38024081, 2023). "Thus, CP and CTP supplements may represent an effective therapeutic approach for age-associated sarcopenia by increasing IGF-1 and decreasing myostatin expression." (PMID 35566067, 2022). "In summary, these results suggest that 12 weeks of circuit exercise could bepresented as an effective way to improved sarcopenic obesity and enhance healththrough improvement of body composition, cardiovascular risk factors,inflammatory markers, and IGF-1 in elderly obese women with sarcopenia." (PMID 39076242, 2022). "In addition, IGF-1, whose concentration in plasma is stimulated by food intake, is associated with the loss of skeletal muscle mass, which probably plays a crucial role in the progression of sarcopenia." (PMID 35892736, 2022). "Besides low serum levels of testosterone, a decreased IGF-1 level has been demonstrated as one of the potential risk factors for sarcopenia because IGF-1 contributes to the proliferation of satellite cells and increases muscle protein synthesis via the activation of the Akt/mTORC1 signaling pathway." (PMID 33803020, 2021). "Therefore, improving intakes or rectifying micronutrient deficiency could potentially affect both the onset of sarcopenia as well as sex hormone and IGF-1 metabolism, via a number of mechanisms, during aging." (PMID 32443563, 2020). "A diet-induced NAFLD mouse model has shown that NAFLD is associated with sarcopenia, decreased muscle strength, and reduced insulin-like growth factor-1 (IGF-1) serum levels, suggesting that IGF-1 reduction may be involved in the pathogenesis of NAFLD-associated sarcopenia." (PMID 29387723, 2017). "This study aimed to evaluate the correlation between inflammatory biomarkers such as C-reactive protein (CRP), tumor necrosis factor-alpha (TNF-α), interleukin-6 (IL-6), and the anabolic hormone insulin-like growth factor-1 (IGF-1) with sarcopenia." (PMID 42267078, 2026). "This condition is also associated with diminished muscle mass, muscle strength, and sarcopenia and a mildly increased GH and IGF-1 level." (PMID 39137152, 2025).
sarcopenia (continued). "The difference was statistically significant, indicating that exercise intervention can significantly increase the serum IGF-1 concentration in older adults with frailty and/or sarcopenia." (PMID 40917423, 2025). "Aging is associated with a progressive decline in circulating insulin-like growth factor- 1 (IGF- 1) levels in humans, which has been implicated in the pathogenesis of sarcopenia." (PMID 40199795, 2025). "A large cross-sectional study among older adults (n ≈ 3276) demonstrated significant differences in IGF-1 levels between the group with sarcopenia and the healthy control group." (PMID 41303670, 2025). "All 11 included articles (including 16 RCTs) adopted exercise as the intervention measure to explore its intervention effect on the serum IGF-1 content in older adults with frailty and/or sarcopenia." (PMID 40917423, 2025). "It suggests that in men, sarcopenia is more influenced by myostatin and serum triglycerides, whereas in women, it is driven by anabolic decline, particularly reduced IGF-1 levels, and nutrition." (PMID 40284239, 2025). "Despite convincing population data, evidence for the effectiveness of systemic IGF-1 therapy in age-related sarcopenia is still insufficient." (PMID 41303670, 2025). "This underscores the need for further clinical research aimed at developing therapeutic strategies based on the modulation of IGF-1 signaling in sarcopenia." (PMID 41303670, 2025). "•Cirrhosis and sarcopenia lower serum IGF-1, highlighting their combined impact on liver function and reserve." (PMID 39624154, 2025). "This protocol delineates a structured approach to evaluate the combined effects of RT and VT on the IGF-1/PI3K/AKT/FOXO3 signaling axis in an older population diagnosed with sarcopenia." (PMID 41004429, 2025). "In this study, we investigate the impact of RT combined with VT on the IGF-1/PI3K/AKT/FOXO3 axis in patients with sarcopenia." (PMID 41004429, 2025). "In summary, as an important factor regulating bone and muscle metabolism, the decline in IGF-1 levels associated with aging, reduced exercise, malnutrition, and other factors may be one of the pathological bases for the development of older adult frailty and sarcopenia." (PMID 40917423, 2025). "The purpose of this study is to systematically evaluates the effects of exercise interventions on serum IGF-1 levels in older adults with frailty and/or sarcopenia using a meta-analysis approach." (PMID 40917423, 2025). "Overall, impairment in anabolic signaling in sarcopenia, as evidenced by suppressed IGF‐1/AKT/mTOR pathway." (PMID 39764565, 2025). "In a case report, a 91-year-old male patient with sarcopenia showed a significant increase in plasma IGF-1 concentration after 3 months of low-intensity BFRT (30% 1RM)." (PMID 40926887, 2025). "In this study, through the Meta-analysis method, we summarized multiple RCTs on the effect of exercise intervention on serum IGF-1 concentration in older adults with frailty and/or sarcopenia." (PMID 40917423, 2025). "The results showed that exercise intervention can help increase the serum IGF-1 concentration in older adults with frailty and/or sarcopenia." (PMID 40917423, 2025). "A possible biomarker of sarcopenia is the reduction in the circulation of IGF‐1 levels in the body, which is often related to sarcopenia and is an indicator of sarcopenia in older adults." (PMID 40937507, 2025). "Exercise intervention can effectively increase serum IGF-1 concentrations in older adults with frailty and/or sarcopenia." (PMID 40917423, 2025). "Meta-analysis revealed that exercise interventions significantly increased serum IGF-1 levels in older adults with frailty and/or sarcopenia (SMD = 0.42, 95% CI: 0.23–0.60, p < 0.0001, I2 = 15%)." (PMID 40917423, 2025).
sarcopenia (continued). "Subsequently, we found that reducing the expression of IGFBP5 partially alleviated fibrosis in sarcopenic muscle by moderately potentiating the effects of IGF-1, providing clue to the development of novel anti-fibrosis therapies in sarcopenia." (PMID 40144669, 2025). "For example, miR-1, uniquely expressed in sarcopenia models, inhibits IGF-1, reducing miR-1 expression by 50%, and has been shown to increase muscle hypertrophy, confirming its role in this pathway." (PMID 39683426, 2024). "An important finding of our study are the low values of IGF-1 calculated in the sera of RA patients with sarcopenia." (PMID 39463868, 2024). "Several variables, including nutritional inadequacies, IR, changes in systemic and/or muscular levels of IGF-1, and inflammatory proteins can disrupt muscle homeostasis during acute or chronic diseases including sarcopenia." (PMID 39186818, 2024). "We predicted for the increase in IGF-1 levels due to sarcopenia by genetic variation, and analyzed the possible reasons." (PMID 39507055, 2024). "Aging itself, along with its inherent hormonal changes in testosterone, estrogen, Growth Hormone (GH), IGF-1 (somatomedin C) levels, and vitamin D, is among the many mechanisms related to sarcopenia." (PMID 39598182, 2024). "This study aimed to investigate the effects of Ophiocephalus striatus extract on insulin-like growth factor-1 serum, interleukin-6 serum levels, and sarcopenia-related parameters in older adults with sarcopenia." (PMID 38525752, 2024). "In sarcopenia, changes in miRNA expression directly or indirectly affect key signalling pathways, including IGF-1, AMPK, mTOR, and PTEN." (PMID 39683426, 2024). "IGF-1 is a circulating growth factor that promotes anabolic pathways in skeletal muscle and prevents age-related sarcopenia." (PMID 38175727, 2024). "The secretion of IGF-1 declines continuously with age, and low IGF-1 is associated with impaired nutritional status and weight loss, frailty, sarcopenia, osteoporosis, and inflammation." (PMID 38396692, 2024). "ROC analysis revealed IGF-1 as a possible predictor of sarcopenia in the RA (AUC=0.675, 95% CI: 0.545–0.804), p=0.008 and an overall model quality of 55%." (PMID 39463868, 2024). "Assessing IL-6 and IGF-1 as the primary biochemical markers of sarcopenia was driven by their accessibility in terms of measurement in Palembang." (PMID 38525752, 2024). "In order to treat sarcopenia, the injection of insulin, growth hormones (hGH and IGF-1), testosterone, and epinephrine led to improved protein synthesis in muscle." (PMID 39409095, 2024). "The reverse study demonstrates a positive correlation between sarcopenia and IGF-1, as well as IGFBP-1." (PMID 39507055, 2024). "In patients with sarcopenia, insulin-like growth factor 1 (IGF-1) mRNA levels decrease by 45% and AKT phosphorylation by approximately 30%." (PMID 39125931, 2024). "IGF-1 and IGFBP3 blood concentrations were found to be reduced in older adults with sarcopenia and were significantly associated with muscle mass and IHG strength." (PMID 38616362, 2024). "In multivariate analysis, severe sarcopenia (OR 4.59; 95% CI 1.21, 17.46, P = 0.025) and IGF-1 levels (OR 0.98; 95% CI 0.96, 0.99, P = 0.023) were independently associated with fragility fracture." (PMID 37775530, 2023). "Em relação aos marcadores humorais e inflamatórios, não houve diferença significativa nas médias para os níveis séricos de PCR-as, IL-6, TNF-α, IGF-1 ou testosterona total entre os grupos com e sem sarcopenia ( Tabela 2 )." (PMID 37556651, 2023). "Looking for mechanisms responsible for sarcopenia in a sex-dependent fashion, it was proposed that a decrease in IGF1 contributes to the development of sarcopenia only in women." (PMID 36902081, 2023). "In particular, the decrease in estrogen concentration associated with aging results in increases in pro-inflammatory cytokine concentrations and a reduction in that of IGF-1, which induces protein synthesis, exacerbating sarcopenia." (PMID 37566094, 2023).
sarcopenia (continued). "In older individuals with sarcopenia, serum growth hormone (GH) levels and insulin-like growth factor (IGF-1) levels are decreased." (PMID 37755537, 2023). "Other factors, such as chronic inflammation, hyperammonemia, alterations in sex hormones, and insulin-like growth factor-1 signaling may also interfere with the glucose disposal in skeletal muscles and lead to muscle loss, which helps to explain the co-existence of sarcopenia with MAFLD." (PMID 36909338, 2023). "IGF-1 levels and IGF-1R signaling are suppressed in many chronic disorders, including age-related sarcopenia, possibly causing muscle atrophy due to the combined effects of altered protein synthesis, UPS activity, autophagy, and impaired muscle regeneration." (PMID 35011721, 2022). "It has also been reported that low serum IGF-1 levels increase the likelihood of developing sarcopenia." (PMID 36078393, 2022). "Decreasing levels of lncIRS1 in the atrophy model induce sarcopenia by impairing the IGF-1 signaling pathway." (PMID 35053303, 2022). "It indirectly lowered the levels of the growth hormone (GH) and insulin‐like growth factor‐1 (IGF‐1) and reduced protein synthesis, leading to sarcopenia." (PMID 35309153, 2022). "Thus, human sarcopenia may be associated with decreased activity of IGF-1 and Akt." (PMID 35250869, 2022). "The supplementation of IGF-1 showed a higher reduction of both histological steatosis and sarcopenia, also favoured by a safer metabolic profile compared to GH intake." (PMID 35052859, 2022). "Among patients receiving HD, serum IGF-1 levels were found negatively correlated with sarcopenia, whereas myostatin levels correlated positively with sarcopenia." (PMID 35682722, 2022). "Indirectly, the concentrations of growth hormone (GH) and insulin-like growth factor-1 (IGF-1) have lowered, with decreased protein production and sarcopenia." (PMID 36013312, 2022). "Clinical studies reported aerobic exercise in people with sarcopenia increases IGF-1 and decrease muscle RING-finger protein-1 (MuRF-1), myostatin, and TNF-α." (PMID 35250869, 2022). "The supplementation with IGF-1 has a higher effect on sarcopenia compared to GH supplementation, probably due to an intrinsic resistance of muscle when chronically exposed to supraphysiologic levels of GH." (PMID 35052859, 2022). "The patients' IGF-1 levels were negatively correlated with sarcopenia status (r = -0.604, p < 0.001)." (PMID 35371569, 2022). "Conversely, the expression of the IGF-1 receptor increases with aging, possibly as a compensatory response to lower IGF-1 levels, leaving open the question as to why mTOR activation is enhanced in sarcopenia." (PMID 36430301, 2022). "Coapplication showed a synergistic effect on suppression of type I fiber atrophy, with significantly higher IGF-1, MyoD, MyoG mRNA (p < 0.05) and pAkt protein expression (p < 0.0001) during sarcopenia." (PMID 36361730, 2022). "Biomarkers associated with nutrition (including albumin, vitamin D, and IGF-1) can be used to evaluate nutritional status and muscle mass, strength, and function in individuals, aiding in the identification and treatment of sarcopenia." (PMID 35892736, 2022). "In human muscle, irisin, IGF-1, FNDC5 (which encodes the irisin precursor) increase after exercise, and irisin is independently associated with sarcopenia." (PMID 35250869, 2022). "Correlation analyses showed that IGF-1 levels negatively correlated with sarcopenia status in elderly patients undergoing hemodialysis (p < 0.05)." (PMID 35371569, 2022). "In the present study, we also measured the serum levels of IGF‐1 and myostatin as potential contributors to the development of sarcopenia." (PMID 35142082, 2022). "In people with sarcopenia, exercise increases IGF-1/PI3K/AKT levels and subsequent mTOR activation to induce protein synthesis, while simultaneously suppressing FOXO signaling." (PMID 35250869, 2022).